BRAF (B-Raf proto-oncogene, serine/threonine kinase)
Diseases named in the same sentence as BRAF in open-access papers (continued):
Sharing a sentence is not in itself a finding about the gene and the disease.
melanoma (continued). "Interestingly, a phase I trial investigating MK-2206 in combination with paclitaxel and carboplatin for the treatment of two patients with BRAF-wild-type stage IV melanoma reported long-term, enhanced responses to chemotherapy [NCT00848718]." (PMID 37181747, 2023). "At first, the lesion may be latent, but later alterations in proliferation genes, such as BRAF, lead to its progression to melanoma in situ." (PMID 36834954, 2023). "In the case of BRAF inhibitor resistance in melanoma, for example, this speciation event may occur through activation of RTKs like IGF-1R or through engagement of the PI3K pathway via PTEN inactivation." (PMID 36853375, 2023). "Specifically, the known key oncogenic mutations in melanoma including, BRAF V600E and NRAS Q61L/R, do not have the UV-signature." (PMID 37697436, 2023). "Therefore, the MAPK pathway is currently the primary target in melanoma treatment, mainly with BRAF-inhibitors (BRAFi), such as vemurafenib." (PMID 37511073, 2023). "MAPK subtype: in melanoma patients, the MAPK (mitogen-activated protein kinase) pathway, is hyperactivated causing a cascade activation of NRAS, BRAF, MEK, and ERK (MAPK), intensifying the transcription of the genes involved in cell proliferation, growth, and mutation." (PMID 36676131, 2023). "In addition, the combination of immunotherapy and other targeted kinase inhibitors will also bring new and effective treatment plans for the treatment of BRAF-mutant melanoma." (PMID 36551302, 2022). "Melanoma mol-GPA (molecular GPA; Graded Prognostic Assessment) is composed of five factors: age, Karnofsky Performance Score (KPS), presence of extracranial metastases, number of brain metastases, and BRAF mutation status." (PMID 36497248, 2022). "More than half are BRAF-positive melanomas, 90% of which have BRAFV600E substitutions." (PMID 35956175, 2022). "In conclusion, the combined assessment of metabolic changes using HP 13C pyruvate and 13C -glucose fluxomic could constitute an ideal multi-modal approach to assess response to BRAF/MEK inhibition in melanoma with specificity and sensitivity." (PMID 35327519, 2022). "Thus, the identification of novel drugs that can induce melanoma cell death at a high rate and/or are effective against BRAF inhibitor‐resistant melanoma is required." (PMID 36282887, 2022). "Grouping melanomas by BRAF or NRAS status did not indicate that driver mutations play a role in the regulation of the MCUA expression (Fig EV1P and Q)." (PMID 36156348, 2022). "In the KEYNOTE-022 phase 2 randomized trial, the combination of pembrolizumab with BRAF/MEK targeted therapy for the treatment of patients with BRAF(V600)-mutant melanoma led to substantial improvement in prognosis; however, it was also linked to a higher incidence of toxicity." (PMID 35493449, 2022). "Finally, public transcriptomic databases were used to validate the role of the HMOX-1 gene in response to BRAF inhibitor treatment in melanoma xenograft models and patients." (PMID 35053476, 2022). "Targeting HMOX-1 could be a novel method for treating melanoma patients who develop BRAF inhibitor resistance." (PMID 35053476, 2022). "BRAF inhibitors have been approved for the treatment of melanoma." (PMID 35847022, 2022). "Patients with advanced melanoma had a threefold increased risk of death over a 7.6-year follow-up period due to a more rapidly progressing disease compared with melanoma without BRAF mutations." (PMID 35456332, 2022).
melanoma (continued). "After administration of a BRAFi in a BRAF-mutant melanoma model, CD40 ligand and interferon-gamma expression was increased on intratumoral CD4+ tumor-infiltrating lymphocytes (TIL), and regulatory T-cells and myeloid cells were decreased, suggesting anti-tumor modulation of the TME." (PMID 36505793, 2022). "Interestingly, simultaneous inhibition of tyrosine phosphorylation of EGFR and SRC kinases can overcome the frequently developing BRAF resistance in melanoma." (PMID 35208960, 2022). "More than 10 different drug types have been approved by the FDA for the treatment of melanoma, including dacarbazine chemotherapy, BRAF and MEK-targeted therapy, recombinant interferon alpha-2b and IL-2, immune checkpoint inhibitors (ICIs), and oncolytic viral therapy (T-VEC)." (PMID 35495634, 2022). "As previously published for mUsp27xS, the large hUsp27xL protein could also stabilize Bim in the BRAF-V600E positive WM1158 melanoma cell line." (PMID 35044632, 2022). "These inhibitors target the constitutively activated MAPK pathway in BRAF mutant melanomas." (PMID 35379799, 2022). "In the context of melanoma, prevalent mutations in BRAF, NRAS, MEK, and KIT oncogenes have already made possible the development of specific targeted therapies directed at the MAPK/ERK pathway, often constitutionally activated in melanoma." (PMID 36143375, 2022). "Taken together, the drug screen and subsequent validation studies suggest that the HMGCRi, STN, could be a potent combination treatment for improving the efficacy of IACS treatment against BRAFi/MEKi-resistant, BRAF-mutant melanomas." (PMID 35193687, 2022). "In a pooled analysis from four clinical trials, enrolling patients with tissue confirmed BRAF V600E/K mutant melanoma; copies of mutant BRAF were identified in 76% (V600E) and 81% (V600K) of 732 baseline plasma samples using BEAMing (beads, emulsion, amplification)." (PMID 35133615, 2022). "Taken together, their results provide the evidence that the [131I]ICF01012 and MEKi combination can be beneficial for the treatment of the advanced pigmented BRAF-mutant melanoma and that [131I]ICF01012 alone is promising for the treatment of NRAS-mutant melanoma." (PMID 36076924, 2022). "The expression of cGMP phosphodiesterase PDE5A is downregulated by oncogenic BRAF in BRAFV600E mutated melanoma by the extracellular-signal-regulated kinase (ERK) pathway, which induces an increase in [Ca2+]i, stimulating melanoma cell invasion and short-term and long-term lung colonization." (PMID 35162934, 2022). "Finally, we evaluated the response of MEK1 Q56P melanoma cells grown in 3D tissue culture to combination MEK/BRAF inhibitor treatment." (PMID 36358868, 2022). "Recent studies provide evidence that mTOR inhibitors may represent a supplementary weapon in the quiver of melanoma treatment alongside with a combination of BRAF and MEK inhibitors." (PMID 35163615, 2022). "Finally, because MEK1 mutation is associated with both BRAF and MEK inhibitor resistance in BRAF V600E melanoma, we also tested the MEK1 Q56P A375 melanoma model for resistance to the FDA-approved MEK inhibitor compounds trametinib and binimetinib." (PMID 36358868, 2022). "BRAF mutation is the most common MAPK pathway aberration, occurring in 40-60% of melanoma cases." (PMID 35440004, 2022). "Functional studies of the effects of tyrosine kinase receptors on the sensitivity of melanoma cells to BRAF/MEK inhibitors indicate that these proteins may be involved in generating resistance to these drugs." (PMID 35565444, 2022). "In BRAF V600E melanoma cells, altered lipid metabolism could contribute to targeted therapy resistance through the modification of the activation of several lipogenesis pathways." (PMID 35681673, 2022). "However, the importance of these inhibitory proteins in BRAF-mutant melanoma cells is still poorly characterized." (PMID 35580987, 2022).
melanoma (continued). "In contrast, mutations of BRAF and c-kit genes which are involved in human melanoma obviously do not play a role in the oncogenesis of canine digital melanoma." (PMID 35202309, 2022). "HDAC8 mediates BRAF inhibitor (BRAFi) resistance in melanoma cells." (PMID 36231123, 2022). "Activation of the PI3K/AKT/mTOR pathway facilitates melanoma resistance to BRAF and MEK inhibition." (PMID 36497341, 2022). "Additional research using prospective or large retrospective cohorts is necessary to validate whether the use of local radiation therapy in addition to BRAF plus MEK inhibitors improves outcomes in patients with BRAF mutant melanoma with brain metastases." (PMID 36579260, 2022). "Patients with BRAF gene altered melanoma who received BRAF and MEK inhibitors (BRAFi/MEKi) may achieve high response rates; however, immunotherapy usually results in durable responses." (PMID 36698407, 2022). "Thus, overexpression of USP22 resulted in resistance to the BRAF inhibitor vemurafenib through the stabilization of YAP and opened new therapeutic avenues for combined inhibition of USP22/YAP and BRAF as an option for melanoma treatment." (PMID 35884430, 2022). "Additionally, a non-BRAF-mutant melanoma cell line (Ma-Mel-103b) was also studied in parallel, to identify the possible effects of vemurafenib, alone or in combination, on cells lacking the targeted mutation." (PMID 36726591, 2022). "BRAF inhibitors are used extensively in BRAFV600E melanomas with positive treatment results." (PMID 36530921, 2022). "Because BRAF-mutated tumors also exhibit the overexpression of genes associated with immunosuppression, such as CTLA-4 or PD-L1, immune checkpoint inhibitors, anti-CTLA-4 and anti-PD-1 have also been approved for the treatment of melanoma." (PMID 36009363, 2022). "Yet, clinical reports have not shown any response of BRAF K601E-mutated melanoma to either BRAFi or BRAFi/MEKi combination therapy." (PMID 35380338, 2022). "Additionally, TAMs secrete TNFα, which promotes MITF expression and inhibits BRAF protein to block apoptosis in melanoma." (PMID 36181568, 2022). "Furthermore, our previous comparative oncogenomic analysis uncovered amplification of dgat1a together with gdf6b (both on chromosome 19) in oncogenic-BRAF-driven zebrafish melanoma, concomitant with up-regulation of dgat1a and gdf6b mRNA." (PMID 35732120, 2022). "The data also suggest that DUSP4 may be critical in maintaining the appropriate level of ERK activity in BRAF-mutant melanoma cells." (PMID 35580987, 2022). "Two patients diagnosed with melanoma of unknown primary by histologic analysis (CUP-34 and CUP-64) harbored two BRAF fusions each, of which CUP-34 also had a BRAF V600E mutation." (PMID 35918329, 2022). "We have observed a similar phenomenon in our previous study with malignant melanoma and treatment with ex vivo BRAF-inhibitor, with some kinases being inhibited, whereas others being activated upon TKI treatment, revealing the complexity of the use of TKIs in the clinics." (PMID 36093296, 2022). "Interestingly, MEK1K57N has been attributed to cause resistance to BRAF and MEK inhibitors in vitro and in patients with melanoma." (PMID 34737188, 2022). "In addition, expression of EXT1, but not SLC35B2, was positively correlated with the YAP1/TAZ score in the TCGA cohort of BRAF mutant melanoma, suggesting that EXT1 is a YAP1/TAZ target." (PMID 35798875, 2022). "In studies of melanoma, BRAF inhibitors can induce autophagy in different ways." (PMID 35719323, 2022). "In addition, it has recently been found that trace element copper is involved in melanoma biology since it is required for BRAF-MEK signaling and when cellular access to it is limited, melanoma cell growth is markedly decreased." (PMID 35955445, 2022). "The most common mechanism for BRAF inhibitors resistance is MAPK pathway reactivation in melanoma." (PMID 36210843, 2022).
melanoma (continued). "BRAFV600 E mutation resulted in altered BRAF protein conformation, increasing its kinase activity, leading to constitutive MAPK pathway activation, resulting in uncontrolled proliferation, cell survival and immune evasion which contribute to melanoma growth." (PMID 35495634, 2022). "Enhanced FN expression is only detected in BRAF inhibitor-resistant PTEN-null melanoma samples." (PMID 35558554, 2022). "Already today, patients with dermal melanoma from AJCC 2017 stage IIIA-D are offered an anti-PD1 therapy, or from stage III A–D with a BRAF V600E or V600K mutation are offered a BRAF and MEK inhibitor, as this prolongs the recurrence-free survival, according to the melanoma guideline." (PMID 35163401, 2022). "The data revealed that at the time of progression, the close association of SOX10+ melanoma cells with CD8+ T cells negatively correlated with PFS of melanoma patients and may indicate a potential mechanism for acquired resistance to BRAF/MEK-targeted therapy." (PMID 35058553, 2022). "Vemurafenib is a selective RAF inhibitor utilized in patients with BRAF-mutant melanoma." (PMID 35846375, 2022). "PD-1 blockade is also effective in patients with BRAF-mutant melanoma; 6.5-year OS rates in CheckMate 067 were 57%, 43%, and 25% in patients with BRAF-mutant tumors and 46%, 42%, and 22% in those with BRAF-wild-type tumors in the combination, nivolumab, and ipilimumab groups, respectively." (PMID 36058945, 2022). "Accordingly, melanomas in the military population would be less likely to originate from the BRAF pathway when compared to the general population, which was our hypothesis, though this has not been established prior to this study." (PMID 35712493, 2022). "Activating mutations in BRAF and NRAS are present in 50% and 25% of melanomas, respectively, and NF1, a protein that inhibits the RAS pathway, may also be inactivated in another 14% of melanomas." (PMID 36402789, 2022). "We observed the same pattern in both the BRAF mutant melanoma cells." (PMID 35956175, 2022). "Overall, our findings reveal that lipid metabolism affects melanoma sensitivity to BRAF inhibitors and that extracellular lipid availability may influence tumor cell response to treatment, a relevant finding in the frame of personalized therapy." (PMID 35912092, 2022). "In addition, SIRT5 was essential for tumordevelopment in both melanoma mouse xenografts and the autochthonous BRAF PTEN-driven melanoma mouse model." (PMID 35802779, 2022). "For examples, the BRAF inhibitor vemurafenib upregulates EMT gene expression in BRAF or NRAS mutated melanoma cells and promotes cell invasion and metastasis 50; the BRAF inhibitor PLX4032 enhances EMT in BRAF inhibitor-resistant thyroid cancer cell line 8505C cells." (PMID 36276640, 2022). "Meanwhile, in BRAF-wildtype and BRAF-melanoma cell lines, miR-210 and miR-155 could promote glycolysis and inhibit oxidative phosphorylation in metabolic conditioning to trigger the reprogramming and the formation of CAFs." (PMID 36499102, 2022). "Dacarbazine was formerly a conventional therapy for patients with previously untreated melanoma who did not have a BRAF mutation and, following dacarbazine therapy, had a median overall survival of 5.6-7.8 months." (PMID 36407184, 2022). "In patients with melanomas harboring the BRAF V600E mutation, immunomodulatory lipids and long chain fatty acids were significantly increased post-BRAF inhibitor (BRAFi) therapy in the non-responder cohort." (PMID 35565240, 2022). "Vemurafenib (VMF), an approved BRAF inhibitor for melanoma, was also approved for LCH." (PMID 36556292, 2022). "Other gene signatures have been proposed to predict the prognosis of melanoma patients with and without BRAF V600E mutation." (PMID 35044091, 2022). "Thus, glutamine addiction is a hallmark of melanoma that can be triggered by resistance to BRAF inhibitors, and its consumption as an energetic substrate facilitates melanoma cell growth via energy-producing TCA cycle anaplerosis." (PMID 35912100, 2022).
melanoma (continued). "Fibroblast-specific production of CCN2, whose overexpression in melanomas was independent of BRAF mutational status, signals through integrins and was found to be essential for neovascularization and vasculogenic mimicry." (PMID 35326670, 2022). "Interestingly, ICI plus BRAF-targeted therapy is promising in melanoma patients, but the safety of this combined regimen is warranted." (PMID 36543792, 2022). "Interestingly, this interaction is conserved among the RAF protein kinase family since BRAF/MITF and CRAF/MITF complexes were also observed in the cytosol of NRAS-mutated mouse melanoma cells." (PMID 35091687, 2022). "Melanoma cell line A375 is a homozygous genotype with BRAF-V600E." (PMID 35468792, 2022). "Patients with resectable BRAF-mutant stage III melanoma who received concurrent treatment with Dabrafenib+Trametinib+Pembrolizumab triple combination therapy in a new phase II trial had a high pathological response rate (80%) and a pathological complete response of 50%." (PMID 36232957, 2022). "Dabrafenib/trametinib treatment helps melanoma cells escape from the microenvironment, which may be a predictor of the effectiveness of dual BRAF/MEK (mitogen-activated protein kinase kinase) inhibitors in treating melanoma." (PMID 36601121, 2022). "To investigate the role of DUSPs in transdifferentiation of metastatic melanoma cells and their response to MAPKi, we selected two BRAF(V600E) mutant human metastatic melanoma cell lines––MRA5 is intrinsically resistant to both BRAFi and MEKi, while MRA6 is sensitive to both inhibitors." (PMID 35999349, 2022). "Furthermore, inhibition of BRAF in susceptible cells results in downregulation of NAMPT transcription, whereas increase of NAMPT expression makes melanoma cells resistant to BRAF inhibitors." (PMID 36160449, 2022). "Likewise, co-treatment of mice bearing BRAF V600E-driven melanoma with CSF-1R- and PD1-blocking antibodies increased efficacy when compared to single agent treatments, most likely due to the capacity of melanoma cell-derived CSF-1 to enhance TAM recruitment." (PMID 36175961, 2022). "The BRAF signature may better help guide targeted therapy for melanoma, and such a framework can be applied to other cancers and mutations to provide more information than mutation status alone." (PMID 35044091, 2022). "In addition, we observed that SEMA6A regulates actin cytoskeleton remodeling, thereby sustaining proliferation and survival of BRAF-mut melanoma cells." (PMID 35440004, 2022). "Another phase I trial (NCT02130466 or KEYNOTE 022) with an anti-PD1 (pembrolizumab) plus dabrafenib and trametinib for BRAF-mutant advanced melanoma, reported an unconfirmed overall response rate of 67% with a high frequency of grade 3–4 treatment-related adverse events." (PMID 36358912, 2022). "In fact,high ERK1/2 phosphorylation levels have been detected in clinical melanomametastases and various melanoma cell lines, and combination of BRAF and mitogen-activated proteinkinase inhibition is the elective treatment in patients with advanced BRAF-mutantmelanoma." (PMID 36046354, 2022). "DEL-22379 was previously shown to trigger apoptosis in melanoma- and CRC-derived cell lines depending on their mutational status, and the cytotoxic effects were more pronounced in BRAF-mutant cells, variable in RAS-mutant cells and negligible in cells wild-type for both oncogenes." (PMID 36056964, 2022). "Dabrafenib and encorafenib showed specific responses in BRAF-positive melanoma cell lines." (PMID 34837846, 2022). "In addition, a therapeutic benefit of adding AXLi to the BRAF-targeted therapy was observed in pre-clinical AXLhigh melanoma models in vitro and in vivo." (PMID 35332208, 2022).